IFITM1 (interferon induced transmembrane protein 1)
Diseases named in the same sentence as IFITM1 in open-access papers (continued):
Sharing a sentence is not in itself a finding about the gene and the disease.
colorectal cancer (continued). "In this study, we find that IFITM1 is essential in migration/invasion of colorectal cancer and is required for the expression of EMT signature in the disease." (PMID 27852071, 2016). "Tissue microarray (TMA) block sections obtained from 232 patients with colorectal cancer were stained with IFITM1 antibody to correlate IFITM1 expression with survival rate and hazard ratio." (PMID 27852071, 2016). "Many studies have shown that Ifitm1 is a marker for colorectal cancer and participates in the tumorigenesis process, and from previous studies, the overexpression of this gene could increase the probability of tumor occurrence." (PMID 40303139, 2024). "IFITM1 expression plays an important role in the invasion and progression of early-stage head and neck cancer and is overexpressed in these tumors; it also promotes metastasis of colorectal cancer." (PMID 31888295, 2019). "Notably, IFITM1 has recently been shown to interact with CAV-1 in colorectal cancer cells, and this interaction impacts the ability of colorectal cancer cells to migrate and invade." (PMID 26897526, 2016). "As IFITM1 has been shown to be increased in cervical, esophageal, ovarian, brain and colon cancers, we analyzed the expression of IFITM1 in multiple patient-derived colorectal cancer cell lines by immunoblot." (PMID 27852071, 2016). "As IFITM1 promotes the invasion of glioma cell lines and head and neck squamous cell carcinoma (HNSCC), we examined whether IFITM1 displays a similar phenotype in colorectal cancer." (PMID 27852071, 2016). "To understand whether IFITM1 is sufficient to drive the migration of cancer cells, we performed a gain of function of IFITM1 in colorectal cancer cells." (PMID 27852071, 2016). "We observed that tumor samples had upregulated IFITMs including IFITM1, IFITM2, and IFITM3, consistent with previous observations in colorectal cancer." (PMID 29088818, 2017). "Nevertheless, our findings position IFITM1 as an important signaling mediator in EMT, which contributes to the progression of colorectal cancer." (PMID 27852071, 2016). "To test whether IFITM1 was involved in the growth of colorectal cancer cells, we determined the proliferation ability using MTT assay after IFITM1 knockdown." (PMID 27852071, 2016). "IFITM1, belonging to the IFN-induced transmembrane protein family, exhibits high expressions in tumor tissues and cells, and it is an independent prognostic biomarker for patients suffering from tumors including gallbladder carcinoma, esophageal adenocarcinoma, colorectal cancer, and gastric cancer." (PMID 36341357, 2022). "As EMT has been implicated in the migration and invasion of cancer cells, we examined whether the migratory defect of colorectal cancer cells in the absence of IFITM1 was related to the expression of EMT signature." (PMID 27852071, 2016). "The proliferation rate of IFITM1-depleted SW620 and HT29 was decreased by about 10∼35% of control cells, suggesting that the proliferation was modestly impaired in the absence of IFITM1 in colorectal cancer cell lines including SW620 and HT29, but not in HCT116." (PMID 27852071, 2016). "SW480, a non-metastatic cell line, exhibited a low level of IFITM1 expression, whereas metastatic cancer cell lines such as HT29, HCT116, and SW620 exhibited a high level of IFITM1 expression, suggesting that IFITM1 might be linked to metastasis and progression of colorectal cancer." (PMID 27852071, 2016).
gastric cancer (13 papers, 2007 to 2024). A primary or metastatic malignant neoplasm involving the stomach. "For example, pathological methylation of the IFITM1 promoter is associated with an elevated level of IFITM1 in gastric cancer and with a metastatic phenotype of ovarian cancer." (PMID 36466909, 2022). "Lee and their colleagues noticed that the IFITM1 affected gastric cancer pathological characteristics through epigenetic regulation." (PMID 37063301, 2023). "Overexpression of IFITM1 and p27 was detected in a cisplatin-resistant gastric cancer cell line (YCC-3/R) compared to parental YCC-3 cells." (PMID 36466909, 2022). "Overexpression of IFITM1 was for the first time found to enhance cancer migration and invasion in 2005, with the cell model of gastric cancer." (PMID 33869009, 2021). "In gastric cancer with high expression of IFITM1, we have demonstrated consistent findings of a beneficial effect on TTR." (PMID 27186374, 2016). "Overexpression of IFITM1 has been reported to correlate with improved survival in glioma and chronic myeloid leukemia but in a South Korean study on gastric cancer, there was a trend towards worse survival in patients with high expression of IFITM1." (PMID 27186374, 2016). "In the entire cohort, IFITM1 was significantly elevated in M0-disease, most notably in gastric cancer." (PMID 27186374, 2016). "In gastric cancer IFITM1 expression had a positive impact on TTR but in esophageal cancer it seemed to have an adverse impact on survival." (PMID 27186374, 2016). "IFITM1 has been demonstrated to promote malignant progression in gastric cancer cells by increasing invasion and migration and by suppressing natural killer cell activity." (PMID 27186374, 2016). "The reason for the diverging prognostic impact of IFITM1 in esophageal and gastric cancer is unclear and warrants further studies." (PMID 27186374, 2016). "There is evidence that IFITM1 overexpression induces tumor resistance to natural killer (NK) cells in gastric tumor cells and it facilitates migration and invasion of gastric cancer cells." (PMID 25588716, 2015). "More recently, there has been increasing evidence to suggest that high expression of IFITM1 plays a role in the progression of several cancers including head and neck cancer, serous ovarian cancer, gastric cancer and colorectal cancer." (PMID 25588716, 2015). "For example, IFITM1 has recently been demonstrated to act as an immune suppressive molecule in gastric cancer cells." (PMID 20707927, 2010). "IFITM1 over-expression in gastric cancer cells was reported to enhance migration and invasion in vitro." (PMID 17868458, 2007). "IFITM1 overexpression is related to the migration and invasiveness of gastric cancer cells." (PMID 39228892, 2024). "In gastric cancer, IFITM1 had a positive impact on TTR, whereas in esophageal cancer, data indicates an adverse impact on survival, suggesting that the role of IFITM1 may differ depending on the tumorigenic pathway." (PMID 27186374, 2016). "An association between high IFITM1 expression and sensitivity to cisplatin has been described in esophageal squamous cell carcinoma whereas in gastric cancer, overexpression of IFITM1 may confer resistance to cisplatin." (PMID 27186374, 2016). "Furthermore, expression of a transcript of CDH1 (E-cadherin) intron 2 (CDH1a) has been shown to increase gastric cancer cell invasion and angiogenesis and this increase correlated with IFITM1 expression." (PMID 27186374, 2016). "The association of high IFITM1 expression and M0-disease, particularly seen in gastric cancer, has to our knowledge not been described previously." (PMID 27186374, 2016). "In addition, there is evidence that IFITM1 overexpression induces tumor resistance to natural killer (NK) cells in gastric tumor cells and it facilitates migration and invasion of gastric cancer cells." (PMID 25588716, 2015). "In addition, epigenetic silencing of the IFITM1 protein has been found in other human malignancies, including gastric cancer." (PMID 26300991, 2015).
gastric cancer (continued). "One of the two RNAs that was significantly higher in cervical compared to gastric cancer was IFITM1, which you may recall was also found to be overexpressed in infected compared to uninfected gastric cancers." (PMID 22929309, 2012). "The seven RNAs upregulated in gastric cancer were CLDN18, EPCAM, REG4, BBC3, OLFM4, PPARG, and CDH17, while the two downregulated genes were IFITM1 and HIF1A." (PMID 22929309, 2012). "However, we could not demonstrate any significant relationship between IFITM1 and OS in gastric cancer, and one possible explanation for this could be the older age in these patients." (PMID 27186374, 2016). "Nine human RNAs were significantly upregulated in EBV-infected compared to EBV negative gastric cancers: FCER2, MS4A1 (CD20), PLUNC, TNFSF9, TRAF1, CXCL11, IFITM1, PPARG, and FCRL3.." (PMID 22929309, 2012).
glioma (13 papers, 2005 to 2026). A benign or malignant brain and spinal cord tumor that arises from glial cells (astrocytes, oligodendrocytes, ependymal cells). "IFITM1 is associated with glioma cell proliferation, migration and invasion, and so may have played a role in the metastatic process in this lesion." (PMID 36937401, 2023). "The phenomenon was then discovered in HNSCC, glioma, and gastric cells in vitro experiments, and meanwhile the downregulation of IFITM1 significantly decreased the activity of matrix metalloproteinase 9 (MM9)." (PMID 33869009, 2021). "A similar contradiction has been described in glioma cells where knockdown of IFITM1 was demonstrated to inhibit proliferation, migration and invasion, whereas reduced expression of IFITM1 correlated with shorter survival in a cohort of 30 glioma patients." (PMID 27186374, 2016). "IFITM1 expression significantly inhibited proliferation, migration, and invasion of glioma." (PMID 27344170, 2016). "However, it is possible that IFITM1 could serve as a negative regulator as it has previously been found to be a negative regulator in certain contexts, with suppression of IFITM1 inhibiting proliferation in glioma cells." (PMID 41378895, 2026). "IFITM1 and IFITM3 expression correlates with poorly differentiated gastric, colon and glioma tumor tissues." (PMID 36466909, 2022). "Previous studies found that IFITM1 gene overexpression can increase cell proliferation, migration, and invasion of esophageal SCC, head and neck cancer, and glioma." (PMID 29051711, 2017). "Functionally, the importance of IFITM1 was reported in glioma cell lines and head and neck squamous cell carcinoma (HNSCC) where IFITM1-depleted cancer cells displayed a lower level of proliferation and invasion." (PMID 27852071, 2016). "In this study on glioma cells, the activation of numerous interferon-induced proteins (such as IFIT1, IFIT2, IFI27, IFITM1, IFITM2, and G1P2) lends support to this mechanism of pathogenicity." (PMID 15829208, 2005). "In recent studies, IFITM1 and IFITM3 were proposed as protumorigenic factors, as knock-down of these proteins inhibited proliferation, migration, invasion and colony formation of glioma cell lines." (PMID 27835870, 2016). "The authors suggest that IFITM1, a homolog of IFITM3, may be produced by glioma cells so as to antagonize the attack by the host immune system by promoting cell proliferation and invasion." (PMID 27835870, 2016).
influenza (13 papers, 2013 to 2025). An acute viral infection of the respiratory tract, occurring in isolated cases, in epidemics, or in pandemics; it is caused by serologically different strains of viruses (influenzaviruses) designated A, B, and C, has a 3-day incubation period, and usually lasts for 3 to 10 days. "IFITM1 encodes interferon-induced transmembrane (IFITM) proteins which are crucial for protection against influenza." (PMID 37630849, 2023). "The main findings of this study were that IFITM1 is downregulated in PBMCs from patients with influenza and is associated with lower survival in these patients." (PMID 35708622, 2022). "We found that the resistance of H820 cells to influenza infection is likely linked to impaired viral entry—due to high basal levels of interferon-induced proteins known to inhibit endocytosis (IFITM1/2/3, NCOA7, and CH25H)—and to increased expression of mRNAs that encode other antiviral factors." (PMID 40434103, 2025). "The IFITM1 gene encodes interferon-induced transmembrane protein 1, which is involved in immune response signaling and has been identified as an antiviral restriction factor for influenza A virus replication; influenza was also diagnosed in the disease challenge model." (PMID 35100362, 2022). "Moreover, recent clinical investigations in humans have linked increased susceptibility to influenza with specific single nucleotide polymorphisms (SNPs) in genes coding IFITM1 and IFITM3 (Everitt and others 2012; Zhang and others 2013; Allen and others 2017; Kim and others 2020, 2021)." (PMID 35708622, 2022). "We next assessed expression levels of various cytokines and chemokines (i.e., IFNB1, IFNL1, IFNL2/3, IFIT1, IFIT3, OAS1, MX1, IL‐6, CXCL10, and IFITM1) which were triggered by influenza and OC43 virus infections alone or together by qPCR." (PMID 38556468, 2024). "In conclusion, the antiviral state induced from prolonged primary HRV infection mediated by RIG-I and ISGs (including MX1 and IFITM1) can confer a protective innate immune defense mechanism against secondary influenza infection." (PMID 37190061, 2023). "IFITM1 and IFITM3 are crucial for protection against influenza, and various single nucleotide polymorphisms altering their function have been linked to disease susceptibility." (PMID 35708622, 2022). "Our human and mice analyses indicate a direct influence of influenza infection on the regulation of bulk IFITM1 and IFITM3 expression in vivo." (PMID 35708622, 2022). "Specifically, influenza samples maintained higher levels of type I IFN response–associated antiviral ISGs (e.g., IFITM1, IFITM2, IFITM3, OAS2, OAS3, OASL) and antigen presentation genes (e.g., HLA-DRB5, HLA-C, B2M, HLA-B, HLA-E)." (PMID 34618691, 2021). "Indeed, the findings from these researchers indicate that IFITM1 acts only during early phases of influenza infection." (PMID 35708622, 2022). "In a related study, >120 host genes were identified that modulated influenza replication and Interferon-inducible transmembrane proteins IFITM1, 2, and 3 were shown to be important in restricting influenza replication, a feature which was also conserved for WNV and DENV infections." (PMID 24275945, 2013). "Influenza, a respiratory illness like SARS-CoV-1 and -2, was expected to lead to differential expression of BST2, IFITM1, and ZBP1." (PMID 39874350, 2025). "IHQ analysis confirmed the little IFITM1 and IFITM3 induction in mouse lungs infected with influenza, showing a restricted expression in some bronchial and alveolar epithelial cells, but not infiltrating leukocytes." (PMID 35708622, 2022). "IFN-stimulated genes (ISG) were also broadly upregulated in lethal disease, including canonical ISGs and genes that have been shown to be important in restricting influenza infection, such as MX1, ISG15 and IFITM1." (PMID 35271686, 2022).
influenza (continued). "IFITM1, 2 and 3-like proteins are already known to have anti-viral function in mammals, with IFITM3 specifically shown to restrict the effects of influenza in a mouse knockout model." (PMID 26238195, 2015). "Using a high-dose murine model of infection, we confirmed not only the downregulation of IFITM1 but also of IFITM3 in the lungs of mice with severe influenza, as opposed to humans." (PMID 35708622, 2022). "As the phenotype of influenza-infected Ifitm3−/− mice is indistinguishable from that of mice deleted for the entire locus (comprising Ifitm1, -2, -3, -5 and -6), Ifitm3 apparently dominates influenza resistance in vivo." (PMID 25614588, 2015). "Hence, in a small subgroup of our influenza cohort from which we could obtain a second sample of PBMCs at intensive care unit (ICU) discharge, we analyzed longitudinal dynamic patterns of IFITM1 and IFITM3 expression and their relationship with the incidence of relevant in-hospital complications." (PMID 35708622, 2022). "Another limitation was the lack of analysis of the genetic variation of IFITM1 and IFITM3 genes and experimental assays of viral inhibition by these genes in specific conditions of infection with influenza A and SARS-CoV-2 virus." (PMID 35708622, 2022).
hepatoma (11 papers, 2012 to 2025). "Previous studies reported that IFITM1 expression is responsive to IFNs α and γ and that downregulation of IFITM1 was detected in cervical cancer and hepatocellular carcinoma." (PMID 39273214, 2024). "Our results were similar to those of a previous study on hepatoma cells, which showed that the overexpression of IFITM1 inhibits cell proliferation." (PMID 29051711, 2017). "In particular, IFITM1 overexpression has been shown to inhibit proliferation in hepatoma cells and its constitutive overexpression has been shown to positively correlate with improved survival in chronic myeloid leukemia patients." (PMID 25588716, 2015). "For example, Hepatitis C virus (HCV) infection enhances miR-130a expression, which in turn inhibits endogenous Interferon-induced transmembrane protein 1 (IFITM1) expression in a hepatoma cell line." (PMID 23202492, 2012). "Collectively, these functional experiments indicate that the tumorigenic properties of hepatoma might be correlated with IFITM1 expression." (PMID 31781559, 2019). "Furthermore, the cellular expression of DEGs from eosinophils such as IFITM1 and S100A9 was associated with the progression of inflammatory‐mediated disease‐driven hepatocellular carcinoma via upregulated mitochondrial oxidative phosphorylation genes (MT‐ND1 and MT‐ND2)." (PMID 41190282, 2025).
lung carcinoma (11 papers, 2012 to 2025). "IFITM1 deficiency suppresses the proliferation, metastasis, and invasion of lung cancer cells." (PMID 35267998, 2022). "Loss- and gain-of Ifitm1 function experiments in lung cancer mouse models might help understanding the role of Ifitm1 in lung cancer development." (PMID 23115618, 2012). "Decreased cyclin D1, β-catenin and c-myc protein levels were detected in the A549 lung cancer cell line after IFITM1 silencing." (PMID 36466909, 2022). "The difference was also observed in two other studies that demonstrated IFITM1 overexpression through tissues and lung cancer cell lines of patients." (PMID 33869009, 2021). "Through the human cancer profiling array containing 10 samples of lung carcinoma and the corresponding normal samples, IFITM1 was detected increasing significantly in lung carcinoma." (PMID 33869009, 2021). "In lung cancer, IFITM1 had the function of facilitating lung cancer cell proliferation and metastasis." (PMID 33968966, 2021). "Accordingly, we find expression of the human IFITM1 gene especially in the normal human bronchial epithelium as well as increased expression in epithelial derived human lung carcinomas based on immunohistochemistry." (PMID 23115618, 2012). "The Ifitm1 expression in mucosa cells of the bronchial epithelium of adult mice is of particular interest in the context of lung cancer, which is responsible for the most frequent cancer associated deaths worldwide." (PMID 23115618, 2012). "Though IFITM2 has not been previously studied in lung cancer prognosis, the related IFITM1 was associated with poor survival in lung adenocarcinoma, contrary to the protective effect of IFITM2 observed in our study." (PMID 36303210, 2022). "This hypothesis is also supported by studies that identified lung cancer related genes in the chromosome band 11p15.5 in man where IFITM1 is located." (PMID 23115618, 2012). "Especially the role of Ifitm1 for lung cancer development and treatment might be in the focus of interest." (PMID 23115618, 2012).